TROAP (trophinin associated protein)
Description:
Could be involved with bystin and trophinin in a cell adhesion molecule complex that mediates an initial attachment of the blastocyst to uterine epithelial cells at the time of the embryo implantation.
Synonyms: TASTIN
Tractability: PROTAC: ubiquitination databases record sites on it.
Gene: Protein-coding gene on chromosome 12 (49,323,216 to 49,331,733, forward strand). Ensembl gene ENSG00000135451.
Subcellular location: Cytoplasm
Gene Ontology:
Molecular function: protein binding
Biological process: cell adhesion
Cellular component: cytoplasm
Genetic constraint (gnomAD): Loss-of-function variants: 63 observed, 85.6 expected, observed/expected ratio (o/e) 0.74, 90% interval 0.6 to 0.91. The upper end of that interval is the gene's LOEUF score, 0.91, which puts it in group 3 of 6, group 1 being the genes least tolerant of losing a copy. Missense variants: 876 observed, 1,021.8 expected, observed/expected ratio (o/e) 0.86, 90% interval 0.81 to 0.91. Synonymous variants: 352 observed, 401.24 expected, observed/expected ratio (o/e) 0.88, 90% interval 0.8 to 0.96.
Homologues: Orthologues: chimpanzee TROAP (99% identical), macaque TROAP (90% identical), dog TROAP (69% identical), pig TROAP (66% identical), guinea pig TROAP (65% identical), rat Troap (53% identical), mouse Troap (52% identical), zebrafish troap (15% identical).
Diseases named in the same sentence as TROAP in open-access papers:
TROAP is named in the same sentence as 44 diseases in open-access papers, as found by Europe PMC text mining. Sharing a sentence is not in itself a finding about the gene and the disease. The quoted sentences say what the papers report.
prostate carcinoma (11 papers, 2019 to 2024). A carcinoma that arises from epithelial cells of the prostate gland. "In our study, we found TROAP promoted PCa metastasis, besides being an independent predictor of risk for new prostate cancer events." (PMID 33995639, 2021). "Our results suggest that TROAP is associated with tumorigenesis and development of prostate cancer." (PMID 33692939, 2020). "At present, several studies have proven that the TROAP is elevated in glioma, liver cancer, prostate cancer, colon cancer, and other tumor tissues, and its expression level is negatively correlated with the survival prognosis of tumor patients." (PMID 37731946, 2023). "The tumor-promoting role of TROAP has been experimentally validated in several preclinical cancer models, including breast, kidney, liver, and prostate cancer." (PMID 37900285, 2023). "In prostate cancer, TROAP also takes part in regulating WNT3/surviving signaling pathways to affect cell progression." (PMID 37731946, 2023). "In prostate cancer, the knockdown of TROAP reduced cell proliferation ability and induced cell cycle arrest and apoptosis, whereas TROAP overexpression led to G1/S phase arrest in LIHC." (PMID 36419876, 2022). "Trophinin-associated protein (TROAP) has been reported to be highly expressed and promotes tumour progression in HCC, prostate cancer, breast cancer, glioma, gastric cancer, and clear cell renal cell carcinoma." (PMID 36217206, 2022). "In recent years, aberrant expression of TROAP has been found to be responsible for the invasive behavior of various malignancies, including breast cancer, colorectal cancer, prostate cancer, gastric cancer, and hepatocellular carcinoma." (PMID 34077623, 2021). "Meanwhile, research shows that TROAP is dysregulated in various tumors such as breast cancer, liver cancer, prostate cancer, and gastric cancer." (PMID 33995639, 2021). "TROAP was upregulated in prostate cancer tissues and predicted the poor survival of prostate cancer patients." (PMID 33500384, 2021). "Recent studies have gradually revealed the oncogenic role of TROAP in several digestive system malignancies, such as prostate cancer, gastric cancer, colorectal cancer, and HCC5–9." (PMID 33500384, 2021). "Data from PRAD also showed that expression of TROAP mRNA was high in prostate cancer with high Gleason scores, high T stages, high N stages and recurrent tumors." (PMID 33692939, 2020). "We performed this study to assess the biological and clinical significance of TROAP in prostate cancer." (PMID 33692939, 2020). "In this study, we used PCA to distinguish the main factor among EZH2, TROAP and E2F1 causing tumorigenesis and development of prostate cancer." (PMID 33692939, 2020). "To assess the expression levels of TROAP mRNA in prostate cancer and normal tissues, we downloaded RNA sequencing data from the TCGA and GEO databases." (PMID 33692939, 2020). "Overexpression of TWIST partially abrogated the inhibitory effects of TROAP knockdown on prostate cancer cells." (PMID 33692939, 2020). "The mRNA data suggested that TROAP expression was markedly upregulated in prostate cancer compared with its expression in normal tissues, especially in cancers with high stages and Gleason scores." (PMID 33692939, 2020). "In this study, we first compared the expression levels of TROAP between prostate cancer tissues and paired normal tissues using data from TCGA and GEO databases." (PMID 33692939, 2020). "We analyzed expressions of TROAP and other genes in prostate cancer tumors at different stages and assessed Gleason scores." (PMID 33692939, 2020). "To identify the potential downstream genes of TROAP we selected 20 genes associated with cancer cell cycles, EMT, or apoptosis and quantified their expression with qPCR in shTROAP and shCtrl prostate cancer cells." (PMID 33692939, 2020).
prostate carcinoma (continued). "Base on the GEO datasets GSE32571, GSE70770, GSE60329 and GSE71016, the results showed that TROAP mRNA is overexpressed in prostate cancer tissues compared with which in normal tissues." (PMID 33692939, 2020). "In all, we identified TROAP as a driver of prostate cancer development and progression, providing a novel target for prostate cancer treatments." (PMID 33692939, 2020). "To further confirm the role of TROAP in the gene regulatory network in prostate cancer, we assessed gene coexpression by qPCR." (PMID 33692939, 2020). "Nonetheless, little is known about the role of TROAP in prostate cancer development and progression." (PMID 33692939, 2020). "In prostate cancers, reduced TROAP expression can inhibit cancer cell proliferation and induce a cell cycle arrest." (PMID 33692939, 2020). "Results from the TCGA prostate cancer (PRAD) database showed similar results with TROAP mRNA being overexpressed in prostate cancer tissues compared with the expression in normal prostate tissues." (PMID 33692939, 2020). "Our experiment results indicate that TROAP could promote prostate cancer development and progression, at least partially, via a TWIST/c-Myc pathway." (PMID 33692939, 2020). "Our results showed that TROAP knockdown could suppress prostate cancer cell migration and invasion by inhibiting TWIST and MMP-9 expressions." (PMID 33692939, 2020). "The results showed that TROAP expression was obviously higher in prostate cancer than in normal prostate tissues, and that it was also higher in prostate cancers with higher Gleason scores, higher T or N stages, and in recurrent cancers than in other prostate cancers." (PMID 33692939, 2020). "We inferred that TROAP might interact with c-Myc, E2F1, and TWIST in prostate cancer cells, but the association among the four genes was unclear." (PMID 33692939, 2020). "All these results demonstrate that TWIST upregulation partially abrogated the inhibition of the effect mediated by TROAP knockdown on prostate cancer cells, which further suggests that TWIST might be a major downstream target regulated by TROAP." (PMID 33692939, 2020). "At the same time, TROAP was shown to be abnormally expressed in some tumor tissues and cell lines, including in prostate cancer, and it could regulate cancer cell biological processes." (PMID 33692939, 2020). "In addition, to explore the functions of TROAP in prostate cancer, we performed gene coexpression analyses with in vitro assays in prostate cancer cell lines." (PMID 33692939, 2020). "However, the mechanisms of TROAP in prostate cancer remain obscure." (PMID 33692939, 2020). "While it was found to be pro-tumorigenic and associated with poor prognosis in most cancer types, including glioma, lung, breast, ovarian, colorectal, gastric and prostate cancer, some studies suggest that high expression of TROAP could predict better survival in acute myeloid leukemia." (PMID 37900285, 2023). "Our integrative mechanism dissection revealed that TROAP is in a pathway downstream of EZH2 and that it activates the TWIST/c-Myc pathway to regulate prostate cancer progression." (PMID 33692939, 2020). "In summary, we observed overexpression of TROAP in prostate cancer when compared with the expression in normal tissues." (PMID 33692939, 2020).
hepatocellular carcinoma (8 papers, 2019 to 2025). A malignant tumor that arises from hepatocytes. "Multiple studies have shown that TROAP expression in breast and colorectal cancer, ovarian adenocarcinoma, hepatocellular carcinoma, gastric cancer and other tumors enhances malignancy and promotes tumor development." (PMID 37298609, 2023). "Additionally, data have shown that elevated TROAP expression positively correlates with the clinical severity of hepatocellular carcinoma, indicating a poor overall and disease-free survival." (PMID 37298609, 2023). "With Western blot and quantitative real-time PCR analysis, we validated TROAP expression levels in hepatocellular carcinoma (HCC) and colorectal cancer (CRC)." (PMID 36419876, 2022). "TROAP was reportedly increased in hepatocellular carcinoma (HCC) and correlated with the degree of malignancies as well as poor prognosis." (PMID 34077623, 2021).
gastric cancer (7 papers, 2019 to 2023). A primary or metastatic malignant neoplasm involving the stomach. "Through downregulated TROAP, the proliferation, cell cycle, invasion, and migration ability of gastric cancer cells could be inhibited." (PMID 37731946, 2023). "TROAP played an oncogenic role in gastric cancer by affecting cell proliferation and invasion." (PMID 33500384, 2021). "TROAP expression was upregulated in gastric cancer (GC) tissues compared with control tissues; thus, high TROAP expression was associated with poor survival in patients with GC." (PMID 31198787, 2019).
glioma (7 papers, 2021 to 2023). A benign or malignant brain and spinal cord tumor that arises from glial cells (astrocytes, oligodendrocytes, ependymal cells). "The majority of immune-related genes were positively associated with TROAP expression in glioma, brain lower-grade glioma (LGG), pancreatic adenocarcinoma (PAAD), and thyroid carcinoma (THCA), LIHC, pan-kidney cohort, and KIRC." (PMID 36419876, 2022). "In our study, we aimed to ascertain TROAP expression in glioma and provide evidence for the oncogenic role of TROAP in the malignant phenotype of glioma and the underlying potential molecular mechanisms." (PMID 34077623, 2021). "We reviewed the clinical characteristics of 70 patients with glioma and explore the association between TROAP expression and the clinicopathological features via immunohistochemistry assay." (PMID 34077623, 2021). "In conclusion, our study revealed that TROAP could promote malignant phenotype of glioma cells in vitro, at least in part, activating Wnt/β‐Catenin signaling pathway, thus proving the role of TROAP and underlying molecular mechanism of TROAP in gliomagenesis for the first time." (PMID 34077623, 2021). "For example, in glioma, TROAP promotes malignant biological behavior and G1/S cell cycle arrest by activating the Wnt/β-catenin pathway." (PMID 36419876, 2022). "Findings showed that TROAP expression was higher in glioma cell lines (especially U251 and SF295) compared to normal astrocyte cells (p < 0.05)." (PMID 34077623, 2021). "Trophinin‐associated protein (TROAP), a soluble cytoplasmic protein characterized by 778 amino acids, showed a cell cycle‐dependent manner, glioma cells with TROAP overexpression represented the accelerated entry into S phase and cell proliferation." (PMID 34077623, 2021). "TROAP knockdown inhibited cell proliferation, migration, invasion, and G1/S cell cycle arrest compared with control group in glioma." (PMID 34077623, 2021). "We hope our findings on TROAP‐induced glioma progress will provide new clues for guiding therapeutic strategies in glioma." (PMID 34077623, 2021). "In the present study, mRNA and protein expression of TROAP was significantly increased in glioma tissues and cell lines, TROAP overexpression was correlated with lower survival rates, which also proved the results of bioinformatic analysis." (PMID 34077623, 2021). "TROAP expression was quantified by qRT‐PCR, western blot and immunohistochemistry assays in glioma tissues and cell lines." (PMID 34077623, 2021). "Based on the bioinformatic analysis and a series of functional assays, we found the TROAP was enriched in glioma tissues and cell lines, its overexpression was correlated with the clinicopathologic characteristics and poor prognosis." (PMID 34077623, 2021). "Then, the results of qRT‐PCR and western blot assays revealed that in comparison with control group, TROAP expression was markedly upregulated with increasing WHO grade in glioma samples (p < 0.05)." (PMID 34077623, 2021). "Meanwhile, analysis using the GEO datasets (GSE4412, GSE16011, GSE52009, GSE4290) indicated that the expression of TROAP mRNA was significantly increased in glioma tissues, especially in GBM, compared to normal brain tissue." (PMID 34077623, 2021). "As previously reported, TROAP could affect the tumor progression and cell cycle of glioma cells via the Wnt/β‐Catenin signaling pathway." (PMID 37731946, 2023). "In contrast, TROAP was anticipated to be a new target for glioma therapy since it could accelerate the malignant growth of gliomas by activating the Wnt/β-Catenin signaling pathway." (PMID 36568384, 2022). "To elucidate the alteration of TROAP expression among multiple types of tumors, we initially analyzed the different mRNA levels of TROAP in several types of central nervous system (CNS) tumors and found that the expression of TROAP mRNA was higher in glioma (GSE501161)." (PMID 34077623, 2021).
glioma (continued). "In our study, the effect of TROAP on biological behavior of glioma cells was investigated." (PMID 34077623, 2021). "The transfection efficiency assays were performed to detect the function of TROAP in glioma cells." (PMID 34077623, 2021). "The present study found that TROAP accelerated the progression of gliomagenesis through Wnt/β‐Catenin pathway, and TROAP might be considered as a novel target for glioma therapy." (PMID 34077623, 2021). "TROAP knockdown and overexpression vector were constructed and transfected into glioma cells." (PMID 34077623, 2021). "Experimental evidence demonstrated a crucial role of TROAP (Trophinin‐associated protein) in regulating the cell proliferation of multiple tumors, while TROAP expression and function were largely unknown in glioma." (PMID 34077623, 2021). "In addition, another study revealed that TROAP could mediate the cell cycle and facilitate the growth of glioma cells by regulating the Wnt/β–catenin pathway." (PMID 37731946, 2023). "Therefore, we speculated that the downregulation of TROAP might be a potential strategy for treating glioma." (PMID 34077623, 2021). "As indicated by western blot, TROAP downregulation using siRNA transfection could result in markedly attenuated cell proliferation, migration and invasion, suggesting that TROAP expression was correlated with the malignant potential of glioma." (PMID 34077623, 2021). "Hence, we speculated that TROAP knockdown inhibited glioma cell proliferation by inducing G1/S cell cycle arrest." (PMID 34077623, 2021). "Similarly, we also analyzed the TROAP expression profiles of patients (LGG and HGG) involved in our study for whom OS data were available, and the results were consistent with the conclusion from TCGA database, suggesting the high level of TROAP indicated poor prognosis of patients with glioma." (PMID 34077623, 2021). "The results revealed that knockdown of TROAP drastically downregulated the level of MMP2, MMP7, MMP9, RHOA, RHOA, ROCK1 protein in U251 glioma cell lines compared to control group (p < 0.05)." (PMID 34077623, 2021). "In addition, we also measured TROAP mRNA and protein level in a normal astrocyte cell line (HA1800) and 5 glioma cell lines (U251, SF295, TJ905, A172, PT2)." (PMID 34077623, 2021).
liver cancer (7 papers, 2019 to 2023). An epithelial or non-epithelial malignant neoplasm that arises from the liver. "The high mRNA expression of pescadillo (PES1), high mobility group A2 (HMGA2), microtubule-associated serine and threonine kinase 2 (MAST2), trophinin-associated protein (TROAP), and MEX3A was associated with poor prognosis for liver cancer." (PMID 32420386, 2020). "Their work verified that high TROAP expression is an independent predictive marker of poor survival in liver cancer." (PMID 31198787, 2019). "Moreover, downregulated TROAP in liver cancer may play a critical role through p21 and p2739." (PMID 32796815, 2020).
breast carcinoma (6 papers, 2016 to 2022). "To validate their functions, we knocked down the expression levels of FAM64A and TROAP in basal-like breast cancer cells and found that the growth of cancer cells was significantly inhibited." (PMID 28489584, 2017). "We conducted RNAi experiments to validate the effect of FAM64A and TROAP in breast cancer cell proliferation." (PMID 28489584, 2017). "The in-silico analysis results suggest that FAM64A and TROAP may promote the development of breast cancer, especially the basal-like subtype." (PMID 28489584, 2017). "However, little is known about the role of TROAP in breast cancer (BC)." (PMID 31198787, 2019). "The trophinin-associated protein regulated by TROAP, has been correlated to aggressive clinico-pathological features including tumour high grade and mitotic rate, while the gene UBE2C has been previously recognised as a prognostic marker for high-risk breast cancer patients." (PMID 27341628, 2016).
colorectal cancer (5 papers, 2019 to 2023). A primary or metastatic malignant neoplasm that affects the colon or rectum. "On the other hand, overexpression of miR-519d impaired colorectal cancer cell viability, migration, and invasion and induced G0/G1 phase arrest and apoptosis by downregulating TROAP expression." (PMID 32616068, 2020). "Some pathways involved in TROAP have been identified in prostate, liver, and colorectal cancers." (PMID 37298609, 2023).
clear cell renal cell carcinoma (4 papers, 2022 to 2025). "For instance, miR-532-3p was down-regulated and reduced the proliferative, invasion, and migration capacities of clear cell renal cell carcinoma cells by binding to TROAP." (PMID 37085288, 2023).